INSR (insulin receptor)
Diseases named in the same sentence as INSR in open-access papers (continued):
Sharing a sentence is not in itself a finding about the gene and the disease.
cancer (continued). "The isoform of the insulin receptor present may be important in the development of cancer." (PMID 23983688, 2013). "However, we can speculate that insulin may modulate cancer development through both the insulin receptor and insulin like growth factor-1 receptor (IGF-1R)." (PMID 20436918, 2010). "The INSR pathway directly impacts cancer development in solid tumors, with insulin and IGF-II activation being prevalent in cancer cells, particularly in dedifferentiated/stem-like cells." (PMID 38731097, 2024). "Insulin receptor (IR) and insulin-like growth factor-1 (IGF-1R) are both critical in the progression of cancer, particularly in tumorigenesis and the development of cancer drug resistance due to cross-talk between IGF-1R and IR signaling pathways." (PMID 39335147, 2024). "In vivo studies have described the overexpression of the insulin receptor, specifically its fetal isoform, in precancerous CRC lesions, supporting the role of insulin in cancer initiation and progression." (PMID 38667278, 2024). "SNHG15, hsa.miR.130a.3p, PTTG1, INSR and HMMR were described in a ccRCC environment, exhibiting the higher expression that induces metastasis and promotes cancer development." (PMID 38673800, 2024). "LRP1 promotes cancer cell migration and invasion by regulating matrix metalloproteinase (MMP) expression and inhibits apoptosis by regulating the caspase and insulin receptor signaling pathway." (PMID 37239055, 2023). "There are several pathways through which metformin works against cancer including through the activation of the PI3K-mTOR signalling pathway, which inhibits the proliferation of cancer cells with insulin receptor expression." (PMID 38275752, 2023). "This trimeric complex plays critical roles in ligand-induced activation of several RTKs, including the EGFR, insulin receptor (IR), the nerve growth factor (NGF) TrkA receptor, and TOLL-like receptors (TLRs), all of which are upregulated in cancer." (PMID 35326525, 2022). "INSR and IGF1R belong to Insulin/IGF System, which was known to affect the malignant behavior of cancer cells and was regulated by Glycans." (PMID 35752862, 2022). "INSR and IGF-1R are frequently overexpressed in cancer cells, where they activate a variety of intracellular signaling cascades that inhibit apoptosis and promote cell cycle progression." (PMID 36295073, 2022). "AG1024 is a reversible, competitive inhibitor of insulin receptor (IR) and insulin-like growth factor 1 receptor (IGF-1R) that induces apoptosis, imparts anti-cancer activity, and significantly delays tumor growth." (PMID 35215353, 2022). "Insulin-like growth factor (IGF) is a potent mitogen that activates the IGF receptor (IGFR)/insulin receptor substrate (IRS) axis, thus stimulating growth in normal cells and uncontrolled cell proliferation in cancer." (PMID 33991522, 2021). "Using our previous F1-γ genome-wide gene expression data (GSE98539), hundreds of mRNAs were predicted as targets of differentially expressed (DE) miRNAs, involved in pathways such as insulin receptor, NFkB and PTEN signalling, linking to apoptosis and cancer." (PMID 33602989, 2021). "The identification of InsR and IGF1R in the nucleus of normal and cancer cells has generated a significant level of interest in recent years." (PMID 33918477, 2021). "In three (3.6%) of the analyzed InsR-expressing PDAC cases (n = 83), a pattern of intense PD-L1 expression in cancer cells was detected." (PMID 34202040, 2021). "These were novel findings that show how insulin and IGF1 downstream signaling cascades differ in cancer cells; however, the mechanisms for these differences were obfuscated by the distance of E-cadherin and ACC from the InsR and IGF1R signaling pathways." (PMID 34191793, 2021). "Insulin receptor (IR) and IGF-1 receptor (IGF1R) play roles in systemic metabolic actions, cell proliferation and migration, as well as cancer growth and metastasis." (PMID 33105604, 2020).
cancer (continued). "Based on previous literature, we have presented a summarized figure where we have shown the common and two well-studied signaling pathways for the insulin and insulin receptor and IGF-1 and IGF-1 receptor as well as for both cancer and diabetes." (PMID 33552973, 2020). "In turn, in cancer cells, IGF1R-, insulin receptor (INSR)- and/or hybrid IGF1R/INSR-independent activity has also been described." (PMID 32977489, 2020). "The insulin receptor (IR) and the IGF-1R, prevalently dysregulated signaling pathways in cancer and DM, have been reported to regulate or be regulated at different levels by ncRNAs." (PMID 31847392, 2019). "By binding to the insulin receptor, insulin activates downstream AKT/mTOR/PI3K and ERK/RAS/MAPK pathways which are involved in cancer proliferation and survival." (PMID 30733504, 2019). "The lack of mutations found in IGF proteins in cancer may hint that INSR/IGF1R signalling is not a key driver in many tumours, and together with cross talk between pathways, this could explain the lack of efficacy seen in clinical trials using several different types of IGF1R‐targeted agent." (PMID 31179642, 2019). "IRS‐1, a key molecule in signal transduction between the insulin receptor and PI3K, was demonstrated to be a target gene of miR‐126 in different cancers." (PMID 31115969, 2019). "The action of metformin on cancer cells depends on a direct effect mediated by AMP kinase and indirect action mediated by circulating insulin to decrease insulin receptor levels together with reduction in AKT and ERK 1/2 phosphorylation." (PMID 29500444, 2018). "Clinically ineffective IGF1R-directed therapies may be associated with the ability of the cancer cell to re-activate the signaling pathway in addition to alternative activation of downstream IGF1R signaling pathways by other growth-promoting receptors in the cell such as HER2/3, EGFR and InsR." (PMID 29207959, 2017). "The autocrine IGF2, in turn, activated insulin-like growth factor 1 receptor (IGF1R), insulin receptor (INSR), followed by PI3K/AKT pathway and RAS/ERK pathway to promote cancer cell proliferation and survival." (PMID 28521298, 2017). "Insulin receptor substrates (IRS), critical components of insulin signaling, are involved in cell proliferation, metabolism, and cancer development." (PMID 27119351, 2016). "Thus, none of the other pathways tested showed any effect upon the E6+UBE3A phenotype, indicating that the effect of the insulin receptor is specific and suggesting that changes in insulin signaling may play a role in in the cell transformation and cancer progression induced by HPV." (PMID 27537218, 2016). "Most human cancers overexpress both the IGF-1 receptor (IGF-1R) and insulin receptor (IR) isoforms, leading to the formation of hybrid IGF-1R/IRs." (PMID 25874233, 2015). "IGF1R and INSRA overexpression increased the migration and invasion potential of all the tested cancer cell lines, while IGF1R and INSR downregulation reduced cell migration and invasion." (PMID 24809298, 2014). "Further work is required (i) to determine the possible role of IGF-1R signalling in VGSC expression/activity in cancer cells, and (ii) to elucidate the possible overlap between the IGF-1R and InsR signalling in this." (PMID 24493753, 2014). "IGF-1R and INSR belong to the IGF signaling pathway, which plays central roles in cell growth, differentiation, survival, cell transformation and cancer metastasis." (PMID 24816813, 2014). "It is reported that the high-affinity insulin receptor (isoform A) binds insulin-like growth factor (IGF)-II with high affinity in fetal and cancer cells." (PMID 24023699, 2013). "Over-expression of the insulin receptor (InsR) and of the closely related IGF1 receptor (IGF1R) is critical for insulin/IGF system over-activation in cancer." (PMID 22558377, 2012).
cancer (continued). "A relationship has been suggested between HMGB1 and cancer based on findings that HMGB1 regulates the transcription of many cancer genes, such as E-selectin, TNF-α, insulin receptor, and BRCA1." (PMID 22496788, 2012). "In cancers such as adenocortical carcinoma and HCC, where insulin receptor binds to IGF ligands with higher affinity, OSI-996 is able to inhibit both insulin receptor and IGF-1R to achieve maximum inhibition of the IGF axis." (PMID 21729319, 2011). "TCPTP is a well-characterized negative regulator of several cancer relevant RTKs including EGFR, cMet, PDGFRβ, Insulin receptor, and VEGFR2." (PMID 20055993, 2010). "Another member of the type II RTK family however, is the insulin receptor (InsR) which shows a high degree of homology with the IGF-1R and has been reported to play a role in cancer development and progression." (PMID 16819546, 2006). "In conclusion, our study provides, for the first time, absolute quantification of RTKs in liver tissue from healthy individuals and cancer patients with a focus on CRLM, reflecting a significant suppression of EGFR, INSR, VGFR3, and AXL, and upregulation of IGF1R, EPHA2 and PGFRB in tumour." (PMID 36890818, 2023). "It has been shown that the A isoform of the insulin receptor (IR-A) is often overexpressed, and its stimulation induces changes in the expression of the insulin receptor substrates (IRS-1 and IRS-2), which are expressed differently in the different types of cancer." (PMID 36975518, 2023). "There is a lack of definitive information on the role of insulin in cancer, and the situation is made more complex by the existence of two insulin receptor isoforms, IR-A and IR-B." (PMID 36975518, 2023). "IRS2 is an insulin-like growth factor-1 receptor (IGF-1R) and insulin receptor signaling transmitter, which may be involved in the PI3K-AKT pathway, leading to the occurrence and progression of malignant tumors and inhibition of apoptosis." (PMID 36277284, 2022). "Generally, INSR is not a deliberate target of cancer therapies, as the implementation of INSR blocking therapies appears particularly problematic given the crucial role of INSR in glucose metabolism." (PMID 35717322, 2022). "Being able to discern differential downstream signaling, we can explore improved anti-IGF1R cancer therapies by eliminating the emergence of compensation mechanisms without disrupting InsR signaling." (PMID 34191793, 2021). "Understanding differences between InsR and IGF1R signaling may aid the development of cancer therapeutics." (PMID 34191793, 2021). "Insulin, insulin-like growth factor-1 (IGF-1), and insulin-like growth factor-2 (IGF-2) are ligands for the transmembrane tyrosine kinase receptors, insulin receptor (IR), and IGF-1 receptor (IGF-1R), which have important roles in growth, development, cancer, and metabolic disease." (PMID 33604295, 2020). "Inhibition of IGF-1 reduces cancer growth and metastasis in some cancers such as pancreatic tumors; however, the role of insulin receptor downregulation in the inhibition of cancer progression has not been fully addressed." (PMID 30987250, 2019). "Vascular insulin receptor expression was always restricted to the cancer site and was never found within adjacent non-neoplastic gastric tissue." (PMID 30989432, 2019). "We hypothesized that mTORC1 inhibition activates the IGF-1R/InsR/IRS-1/2 axis in an ER-dependent manner to drive PI3K/AKT and promote cancer cell survival, implicating ER in survival signaling induced by mTORC1 inhibition." (PMID 29507656, 2018). "Recently, the miR-126 that is known to regulate angiogenesis has been found to control cancer metabolism by targeting the insulin receptor substrate-1 (IRS1).39, 71 IRS1 is an adaptor proteins involved in signaling via insulin receptor (IR) and insulin-like growth factor I receptor (IGF-IR)." (PMID 28104913, 2017).
cancer (continued). "Several studies have reported extensive cross-talk between IR (insulin receptor)/IGF1R (insulin-like growth factor-1 receptor) and EGFR/ErbB signaling pathways contributing to acquired drug resistance in various cancers." (PMID 25599599, 2015). "Resistance to IGF-1R inhibition in other cancers has been attributed to increased INSR signaling; however, we did not observe alterations consistent with such a mechanism." (PMID 25344862, 2014). "Vice versa downregulation of either IGF1R or total INSR decreased cancer cell proliferation while increasing proliferation in non-cancerous cell lines." (PMID 24809298, 2014). "In contrast, INSRB had no impact on cancer cell proliferation, colony formation, migration and invasion potential in vitro suggesting a differential function of the INSR isoforms on PCa cells." (PMID 24809298, 2014). "We now find that XMetS, a positive allosteric modulator of the INSR, also does not agonize or potentiate insulin-mediated cancer cell proliferation." (PMID 24533136, 2014). "We previously reported that XMetA, an INSR agonist antibody, selectively activated metabolic but not mitogenic functions including the proliferation of cancer cells." (PMID 24533136, 2014). "Modulations of only INSRB had no major impact on colony formation ability of cancer cells suggesting that INSRA is the major INSR isoform promoting colony formation ability." (PMID 24809298, 2014). "Signalling by the insulin pathway is highly relevant in cancer development as both extracellular-signal-regulated kinase (ERK) and phosphatidylinositol-3 kinase (PI-3 K) pathways are triggered by activation of the insulin receptor (IR)." (PMID 24073332, 2013). "IR (insulin receptor) is a tyrosine kinase receptor, known to stimulate the AKT pathway, and it has been suggested that the RB/E2F pathway, which is also known to play a role in cancer, has an effect on AKT activity via transcriptional regulation." (PMID 22578440, 2012). "In addition, many cancer cells express insulin receptors (IRs) and show hyperactivation of the IGF1R-IR pathway." (PMID 22029671, 2011). "Our data suggest that different cancer cell lines exhibit differences in cellular uptake of exogenous ARG when cells were treated with both ARG and insulin simultaneously, which did not appear to be associated with the level of insulin receptor expression." (PMID 38374190, 2024). "In addition to integrins, we identified other glycoproteins regulated by B4GALT1, such as neutral amino acid transporter (SLC1A5), insulin receptor (INSR), and growth/differentiation factor 15 (GDF15), which have been reported to modulate cancer malignant phenotypes." (PMID 37907465, 2023). "Finally, it was shown that INSR and LDHA might be used as prognostic markers for developing premalignant lesions to cancer involving glucose metabolism in digestive diseases." (PMID 35755820, 2022). "In addition, the insulin receptor (IR) can be activated by phosphorylated Cav-1 and binds to LDL receptor–related protein 6, thereby mediating the Akt-mTORC1 signaling pathway and regulating aerobic glycolysis in cancer cells." (PMID 34955837, 2021). "Indeed, cancer cells frequently show augmented insulin receptor expression levels, mostly of the isoform A (lacking exon-11), whose activation is more responsible for mitogenic than metabolic effects and also shows high affinity for IGF-2." (PMID 34680546, 2021). "Evidence suggest that insulin stimulates growth mainly via its own receptor and not the IGF-1 receptor, and that in many cancer cells, the insulin receptor is overexpressed and the A isoform, which has a predominant mitogenic effect, is more represented than the B isoform." (PMID 32854644, 2020). "Pathway analysis of our gene array data identified five canonical signalling pathways dysregulated in cancer, namely, Insulin Receptor Signalling, Dolichol and Dolichyl Phosphate Biosynthesis, UDP-N-acetyl-D-glucosamine Biosynthesis II, Ceramide Biosynthesis, and IL-3 Signalling pathways." (PMID 31754384, 2019).
cancer (continued). "However, whereas the IGF1R has been identified as a potential therapeutic target in cancer, such a validation is still lacking for the closely related INSR." (PMID 24434591, 2014). "Moreover, insulin receptor (IR), closely related to IGF-1R, is also overexpressed in many cancers." (PMID 23696913, 2013). "The eIF3D-dependent translation also enabled the synthesis of insulin receptors (INSR) and insulin-like growth factor 1 receptors (IGF1R), and the synthesis of proteins involved in the JAK/STAT pathway in non-dividing cancer cells." (PMID 38418814, 2024). "Unlike INSR expression, which contributes less to tumorigenesis, the malignancy of dysregulated IGF-1R in cancer progression has been investigated, and targeting IGF-1R in cancer treatment is currently under development." (PMID 24816813, 2014). "In addition, INSR and IGF1R are important for energy metabolism, cell growth, and cancer progression, and to our knowledge, no quantitative data have been published for INSR." (PMID 36890818, 2023). "However, cellular studies were not able to reproduce such a result in vitro until a specific isoform of the insulin receptor, lacking 12 aa in the extracellular portion corresponding to exon 11 (IRA), was shown to be the high-affinity receptor for IGF-II in both fetal and cancer cells." (PMID 32033443, 2020).